EGFR (epidermal growth factor receptor)
Diseases named in the same sentence as EGFR in open-access papers (continued):
Sharing a sentence is not in itself a finding about the gene and the disease.
tumor (continued). "EGFR mutations were detected in primary tumor tissues by ARMS-PCR assays, tissue EGFR 19del mutations were identified in 18 cases (60.0%) and EGFR L858R mutations were detected in 12 patients (40.0%)." (PMID 33828979, 2021). "Analysis of the sensitizing—and T790M—EGFR mutant fractions (MFs) was used to determine tumor mutational burden." (PMID 33131198, 2021). "Such feedback should lead to fast amplification of adhesion loss and EGFR activation, promoting invasiveness and proliferation of a tumour." (PMID 35127732, 2021). "Compared with tumor samples, the concordance rate of detecting EGFR sensitive mutations in the sputum cfDNA were 100%, 40.0%, and 25.0% in three sputum groups of malignant, satisfactory but no malignant cells, and unsatisfactory, respectively." (PMID 33932095, 2021). "We found a significantly diminished expression of CD8B mRNA in tumours overexpressing mutant forms of the EGFR, confirming the described effect of the mutated EGFR expression on reducing the CD8 T-cell infiltration in these tumours." (PMID 35052732, 2021). "Most of the EGFR mutations are measured by tumor tissue immunohistochemistry through wounded puncture or surgery." (PMID 34722241, 2021). "Targeted therapy targets specific alterations in NSCLC cells that stimulate tumor growth, for example mutations in the epidermal growth factor receptor (EGFR)." (PMID 34262573, 2021). "Tumor-specific EGFR variant III (EGFRvIII), resulting from deletion of exon 2–7 of wild-type EGFR (wtEGFR), is present in 30% of GBM patients." (PMID 34568006, 2021). "In contrast, another study has found a decreased PD-L1 expression in tumor tissues from NSCLC patients bearing EGFR mutation." (PMID 34113560, 2021). "The re-plasticity of the TME, which is characterized by the infiltration of tumor-associated immune cells and the upregulation of immune checkpoint-related proteins, was also responsible for the resistance to anti-EGFR drugs and treatment failure." (PMID 34858988, 2021). "In glioma, loss of LRIG1 results in very aggressive tumors, though the ectopic LRIG1 expression causes decreased tumor cell proliferation by negatively regulating the oncogenic EGFR mutant EGFRvIII, which is often highly expressed in glioblastoma." (PMID 33786987, 2021). "Several reports have shown that overexpression of the epidermal growth factor receptor (EGFR) is strongly associated with tumor progression, migration, and invasion." (PMID 33709843, 2021). "We evaluated here the performance of the Idylla ctEGFR mutation assay for the detection of EGFR mutations in circulating tumour DNA (ctDNA) in plasma from patients with NSCLC." (PMID 34006948, 2021). "For these cases with EGFR mutations tested by NGS, 65.3% of them also carried tumor-related variants in some non-EGFR genes and about one third of them were considered candidates of targeted drugs." (PMID 34257561, 2021). "The tumour microenvironment of patients with EGFR mutations lacks potent tumour killing effector cells and appears dysfunctional with effector cells." (PMID 33910272, 2021). "In NSCLC, second and third-generation EGFR-TK inhibitors were prepared for tumor cells with the T790M gatekeeper mutation and PI3K/AKT/mTOR inhibitors were under clinical trials." (PMID 34681198, 2021). "The average size of the largest tumor deposit was significantly larger in cases with EGFR mutations (ctDNA-positive) than in cases that were EGFR mutation-negative (ctDNA-negative) (34.10 mm versus 25.76 mm, p < 0.001)." (PMID 34574036, 2021). "In the validation set, 62 tumours (9.3%) showed no expression of NKX2‐1/TTF‐1 exon 1; such tumours were significantly associated with older age, EGFR wild‐type tumours, and poor prognosis." (PMID 34014042, 2021).
tumor (continued). "DUSP4 is a putative tumor suppressor that is located at 8p12, which frequently undergoes a single-copy genomic loss in EGFR mutant LUADs." (PMID 34944063, 2021). "Although the clearance of RAS mutations is a rare event, it is conceivable that subclones with RAS mutations are less fit in the untreated tumor and acquire fitness as a consequence of adaptation to the microenvironment induced by EGFR therapies." (PMID 34745987, 2021). "In this study, tumor‐derived exosomes from the plasma of EGFR mutation and wild‐type NSCLC patients were isolated." (PMID 33682961, 2021). "Acquired resistance can be due to secondary mutations in the target (EGFR) that render the therapy ineffective, activation of bypass signaling pathways to maintain tumor growth, or cellular transformation." (PMID 34642436, 2021). "Depatux-M has shown promising in-vivo activity in tumor models overexpressing wild type EGFR, EGFR amplification, or EGFRvIII mutation." (PMID 34926242, 2021). "First-line treatment options for NSCLC tumours expressing an EGFR activity enhancing mutation include the second-generation small molecule EGFR inhibitor, afatinib." (PMID 34221011, 2021). "EGFR signaling pathway has been confirmed to be aberrantly activated in multiple malignant tumors, which is associated with tumor progression and prognosis." (PMID 35111681, 2021). "A significant association of EGFR expression was noted with tumor grade, mean Ki67 index, axillary metastasis, and nodal (N)-stage." (PMID 34150374, 2021). "Two large meta-analysis studies were conducted to compare cfDNA with tumor tissue in terms of diagnostic accuracy for EGFR mutations." (PMID 34003366, 2021). "NSCLC harboring EGFR mutations exhibited an immune-inert phenotype, which was characterized by low expression of PD-L1, low tumor mutational burden, low cytotoxic T-cell number, and low T-cell receptor clonality." (PMID 34917129, 2021). "Only one patient had an objective response, but repeat analysis of this patient’s tumor definitively showed the original report of an EGFR mutation to be erroneous." (PMID 34208111, 2021). "The response of HNSCC patients to anti-EGFR antibodies varies and seems to be associated with a high degree of tumour heterogeneity." (PMID 34944837, 2021). "AKT and EGFR activate YAP in tumor cells and recruit TIC-associated macrophages (TICAMs) to liver TICS by enhancing Ccl2/Csf1 secretion in the initial stage and also converts hepatocytes to TICs." (PMID 34944765, 2021). "There were different results of the NGS tests between blood samples and tumor tissue samples at the same time, that EGFR T790 M mutation was only found in blood and Met amplification was only found in tumor tissue." (PMID 34397683, 2021). "For example, emergence of a tumor bearing an EGFR T790M mutation in a patient who had disease progression after initial response to gefitinib was first identified in 2005." (PMID 34202748, 2021). "Patients harbored EGFR activating mutations, as detected by tumor biopsy, and were treated with anti‐EGFR TKIs in the first line." (PMID 33942501, 2021). "In regard to radiologic features, tumours with EGFR mutations tended to be smaller than EGFR-wild-type tumours (p < 0.001), and the optimal cut-off value of the tumour maximum diameter was 33 mm." (PMID 33707479, 2021). "Lastly, one patient shared a single EGFR 19Del mutation with one and five unique mutations per tumor." (PMID 34109114, 2021). "We found that EGFR expression in triple-negative MBC signifies poor prognostic significance, as positive EGFR expression was significantly associated with axillary metastasis, higher tumor grade, and higher mean Ki67 index." (PMID 34150374, 2021). "Outgrowth of a TKI-resistant clone after clearance of the T790M-positive subclone was associated with shorter mPFS in NSCLC patients who tended to have a smaller fraction of T790M over the activating EGFR mutation in their tumor at baseline." (PMID 34638411, 2021).
tumor (continued). "For example, 202 NSCLC specimens were screened for EGFR mutations where mutant EGFR tumours were found to harbour higher expressions of MET." (PMID 34298636, 2021). "We applied a rapid and quantitative pipeline for detecting driver EGFR mutations in a retrospective cohort of NSCLC patients using circulating tumor DNA and extracellular vesicles' RNA (EV‐RNA) as independent longitudinal sources." (PMID 33942501, 2021). "Patients who had lost the T790M mutation at progression had significantly shorter PFS and tended to have a smaller fraction of T790M related to the activating EGFR mutations in their tumor at baseline." (PMID 34638411, 2021). "Next‐generation sequencing (NGS) was performed in a clinical trial, and an EGFR K860I mutation was detected in her tumor." (PMID 33942527, 2021). "PD-1 blockade increased the number of tumor infiltrating anti-EGFR variant III (EGFRvIII) CAR T cells leading to enhanced antitumor activity." (PMID 34209505, 2021). "This study also analyzed the clinicopathological features of patients in which sufficient tumor cells were detected in sputum for EGFR mutation testing via ddPCR." (PMID 33757469, 2021). "Ninety-two (67.2%) patients had an EGFR mutation detected in tumor tissue (52 exon 19 deletion, 33 L858R, 3 exon 18 mutations and 4 exon 20 mutations)." (PMID 34680416, 2021). "It was also verified that circulating tumor DNA (ctDNA) in the plasma can be used to detect EGFR mutations in patients with NSCLC, providing information similar to that obtained from biopsies." (PMID 34722241, 2021). "Previously, we examined the morphology and EGFR mutation status of tumor cells in airway secretions collected from segmental or lobar bronchus of surgically resected specimens and compared the results with FFPE tumor tissue." (PMID 33757469, 2021). "EGFR is highly expressed in a variety of tumours, and is associated with tumour occurrence and development and poor prognosis." (PMID 34809653, 2021). "For tumours with mutations in exons 18, 19, 21, and 20 of the EGFR gene, 80% gefitinib is effective 4,5, but it is useless for tumours with EGFR wild-type mutations." (PMID 33707479, 2021). "Considering these scenarios, a microenvironment-mediated downregulation of EGFR and the associated signaling cascades should lead to a downregulation of PD-L1 increasing tumor immunity and the impact of immuno-oncological therapies." (PMID 33718186, 2021). "Licochalcone A inhibited in vitro cell growth, colony formation and in vivo tumour growth of either wild‐type (WT) or activating mutation EGFR‐expressed NSCLC cells." (PMID 33247550, 2021). "Amivantamab was demonstrated to employ three mechanisms to inhibit tumors with diverse EGFR mutations and complete and durable tumor regression was noticed in the combination treatment of amivantamab and a third-generation EGFR-TKI (AZD9291)." (PMID 34922633, 2021). "Specifically, increased PD-L1 expression was associated with wildtype EGFR and vascular invasion, and total PD-L1 mRNA levels correlated weakly with protein expression on tumor cells." (PMID 33956842, 2021). "Alterations characteristic of GBMs were observed in nine out of ten tumour tissues (chromosome 7 gain/EGFR gene amplification n = 9, chromosome 10 loss including PTEN gene n = 8)." (PMID 34282761, 2021). "Molecular cooperation between HIF-1α and c-Jun (c-Jun proto-oncogene) was described in NSCLC tumours harbouring an activating mutation of EGFR, resulting in both primary and acquired resistance to EGFR-TKI." (PMID 34298636, 2021). "Amplification of the mutant EGFR allele alters EGFR protein levels and increases downstream signaling activity, which has been demonstrated to function as a tumor progression event." (PMID 34944063, 2021). "In a previous study, the presence of EGFR mutation L858R expression showed a higher tumor disappearance rate of LADC than the EGFR wild-type." (PMID 33799753, 2021).
tumor (continued). "We observed that LUAD with EGFR mutated have less infiltration of anti-tumor immune cells, including CD8+ T cells, activated CD4+ T cells and M1 macrophages, and increased M2 macrophages infiltration." (PMID 34178613, 2021). "EGFR carries mutations in all tumor regions of GB02 and GB03 while only three regions of GB01 have EGFR mutations." (PMID 33922652, 2021). "Third, the methodology of detecting EGFR mutation differed between surgical resected tumor samples and sputum samples." (PMID 33757469, 2021). "Clinical trial NCT01193829 (Development of Circulating Tumor Cell Molecular Diagnostics Using a Novel Microfluidic Device) aimed at comparing EGFR mutations in primary NSCLC tumors of respective CTCs isolated via a label-free microfluidic device." (PMID 33925308, 2021). "Other groups have instead focused on the detection of mutant and wild-type EGFR overexpression via sEV-packaged RNA in the cerebrospinal fluid of patients, where the mutational status of the parental tumour is accurately represented." (PMID 33228060, 2020). "In NSCLC, the clinical relevance of the EGFR c.2369C>T p.(Thr790Met) variant at a VAF of 1% in a tumor-rich tissue sample is still under debate, and ultimate therapy decisions by the treating physician need to consider the complete clinical patient context." (PMID 32357863, 2020). "Although more and more studies have confirmed the superior efficacy of Osimertinib in NSCLC paitents with EGFR driver mutations 5, 12, 20-22, the tumor response and survival outcomes after the treatment of Osimertinib are usually different in patients." (PMID 32231715, 2020). "In contrast, patients with LEATs demonstrating astrocytic differentiation, BRAF mutation as well as activation of MAPK/FGFR/EGFR oncogene pathways are at higher risk of tumor recurrence and malignant progression." (PMID 31919458, 2020). "Our first studies verified that gefitinib and erlotinib in addition to their primary mechanism of targeting tumor cells harboring mutated forms of EGFR also act as pro-oxidative stressors." (PMID 33198218, 2020). "For most of clinical cases, tumor biopsies are used to evaluate the EGFR mutations and guide the patient treatment." (PMID 33117705, 2020). "In this study, post-treatment hr-HPV positivity was associated with clinical T-stage at diagnosis and tumor EGFR expression." (PMID 32344907, 2020). "In this retrospective study, we performed immunohistochemistry to evaluate EGFR expression and localization in tumor cells, EGFR mutation-specific expression (E746-A750del and L858R), and human papillomavirus expression in a series of 29 conjunctival SCCs." (PMID 32833992, 2020). "For example, tumour location in the colon is associated with response to anti-EGFR agents in the RAS/RAF wild type population." (PMID 33292279, 2020). "The second study consisted of a larger sample size (n = 185) and was consistent with the first study: Sel-Cap detected over two-thirds of EGFR-activating mutations that were detected by PNAclamp in tumor (sensitivity: 72% for Ex19del and 67% for L858R)." (PMID 33266057, 2020). "Through analyzing GC datasets, we revealed YARS’s co-expression with EGFR amplification, specific mutations, tumor mutation burden, EBV/MSI phenotypes, as well as multiple gene sets potentially those were enriched by YARS high expression." (PMID 31912229, 2020). "We have previously reported findings with the first exceptional responder of HNSCC for EGFR inhibitor, whose tumor harbored MAPK1p.E322K mutation, which was then subsequently proven to confer heightened sensitivity to erlotinib in vivo." (PMID 32351709, 2020). "This study provides some of the first evidence for the importance of maintaining high tumour content ratio when testing for EGFR mutations and encourages microscopic tumour dissection with small biopsies." (PMID 32028905, 2020). "This is significant because EGFR overexpression has been observed in multiple tumor tissues and is associated with overall poor prognosis." (PMID 32867363, 2020).
tumor (continued). "One possible reason for this difference is that fewer discrete signaling dependencies exist with NF1 tumor suppressor loss than cancers that are critically dependent on RAS signaling as a result of activating RAS or EGFR mutations." (PMID 32245042, 2020). "Samples with undetected EGFR mutations were retested after tumour dissection and the rate of samples whose EGFR mutation was corrected to positive was assessed." (PMID 32028905, 2020). "The coincidence rate between ddPCR and EGFR gene mutation in tumor tissues was 82.4% (Kappa=0.647, P < 0.001), the sensitivity was 74.1%, and the specificity was 90.2%." (PMID 32093452, 2020). "Deep sequencing analysis of ctDNA enriched for the EGFR L858R mutation revealed the significant presence of EGFR L858R ctDNA as ultra-short circulating tumor DNA (usctDNA) with the size of 40–60 bp in patient plasma and saliva." (PMID 32722209, 2020). "Treatment with EGFR-TKIs causes tumor reduction; however, the progression of cancer occurs at 6 to 12 months after treatment." (PMID 32070026, 2020). "Two commercial EGFR mutation tests approved in Korea, cobas v2 and PANAMutyper, show highly concordant test results in both tumor and plasma samples from NSCLC patients." (PMID 32224854, 2020). "The need for tumor genotyping is thus highly supported at least at time of diagnosis and disease progression on or after first- or second-generation EGFR-TKIs for mutation evaluation." (PMID 32345265, 2020). "Hypo EGFR TKI can induce hypoptosis in tumor cells, releasing tumor-derived danger-associated molecular patterns (DAMPs), that can activate cGAS-STING and Toll-like receptors (TLR)-Myd88, that are essential for type I interferon production." (PMID 32516941, 2020). "Evidence from the literature indicate that Stat3 is activated by epidermal growth factor receptor (EGFR) stress-exposed tumor cells and is associated with a survival advantage for tumor cells (reviewed in Balanis and Carlin)." (PMID 32722178, 2020). "There was also a significant association between EGFR over expression and tumor relapse after adjuvant chemotherapy for advanced BCa, which introduced EGFR as a useful prognostic marker of BCa." (PMID 32795296, 2020). "ROR1 was shown to inhibit apoptosis, potentiate EGFR signaling and reported to be overexpressed and associated with poor prognosis in several tumor models." (PMID 33172431, 2020). "Activation of EGFR by binding with ligand or mutation is essential for tumor cell proliferation, migration and cancer stem cell self-renewal." (PMID 33643898, 2020). "The EGFR mutation was significantly associated with women, non‐smoker, and normal serum tumor markers level (both P < 0.001)." (PMID 32729257, 2020). "We achieved a 100% concordance rate for the detection of EGFR mutation, including emergence of T790M, between tumor tissue and CTCs." (PMID 32373206, 2020). "In GBM, CD151 associates with α3β1 integrin to potentiate EGFR signaling, drive cancer cell motility and tumor aggressiveness." (PMID 32616845, 2020). "TOXlow tumours are associated with the loss of PTEN and amplification of EGFR, while TOXhigh tumours harbor frequent mutations in IDH1 (91%)." (PMID 32762688, 2020). "In this study, we introduce a dual-target system focusing on the tumor-associated antigens EpCAM and EGFR." (PMID 32504247, 2020). "FDG uptake was associated with tumor invasiveness 12, meanwhile EGFR signaling regulated cell proliferation and glucose metabolic pathway in NSCLC with EGFR mutations." (PMID 32742498, 2020). "Recently, EGFR mutations within EP DNA showed a sensitivity of 100% and specificity of 96.55% in comparison with the detection of tumor tissues in lung adenocarcinoma." (PMID 33158181, 2020). "We conducted high-throughput drug screening using PDCs with available EGFR copy number data and observed that EGFR amplification was associated with the anti-tumor effect of GC1118." (PMID 33142709, 2020).